TOR1AIP1 (torsin 1A interacting protein 1)
Description:
Required for nuclear membrane integrity. Induces TOR1A and TOR1B ATPase activity and is required for their location on the nuclear membrane. Binds to A- and B-type lamins. Possible role in membrane attachment and assembly of the nuclear lamina.
Synonyms: LAP1B; LAP1; FLJ13142; LAP1C; LGMD2Y
Tractability: Antibody: UniProt predicts a signal peptide or a membrane-spanning region. PROTAC: UniProt records ubiquitination sites on it; ubiquitination databases record sites on it; its protein half-life has been measured.
Gene: Protein-coding gene on chromosome 1 (179,882,042 to 179,920,077, forward strand). Ensembl gene ENSG00000143337.
Subcellular location: Nucleus inner membrane; Nucleus envelope (Isoform 4); Nucleus
Subcellular location (Human Protein Atlas): Nuclear membrane
Pathways (Reactome):
Signal Transduction: RHOD GTPase cycle; RHOF GTPase cycle
Gene Ontology:
Molecular function: ATPase activator activity; ATPase binding; cytoskeletal protein binding; protein binding; lamin binding
Biological process: positive regulation of ATP-dependent activity; nuclear membrane organization; protein localization to nucleus
Cellular component: nuclear envelope; nuclear membrane; nucleus; endomembrane system; nuclear inner membrane
Genetic constraint (gnomAD): Loss-of-function variants: 14 observed, 25.2 expected, observed/expected ratio (o/e) 0.56, 90% interval 0.37 to 0.87. The upper end of that interval is the gene's LOEUF score, 0.87, which puts it in group 3 of 6, group 1 being the genes least tolerant of losing a copy. Missense variants: 357 observed, 352.63 expected, observed/expected ratio (o/e) 1.01, 90% interval 0.93 to 1.11. Synonymous variants: 154 observed, 149.07 expected, observed/expected ratio (o/e) 1.03, 90% interval 0.9 to 1.18.
Gene-disease validity (ClinGen):
ClinGen rates the evidence that TOR1AIP1 causes each of these diseases.
TOR1AIP1-related myopathy (autosomal recessive): Definitive. A congenital myopathy in which the cause of the disease is pathogenic variation in the TOR1AIP1 gene.
Homologues: Orthologues: chimpanzee TOR1AIP1 (99% identical), macaque TOR1AIP1 (93% identical), dog TOR1AIP1 (79% identical), pig TOR1AIP1 (79% identical), rat Tor1aip1 (71% identical), mouse Tor1aip1 (69% identical), guinea pig TOR1AIP1 (57% identical), tropical clawed frog tor1aip2 (27% identical), zebrafish si:dkeyp-82a1.6 (22% identical), zebrafish zgc:112962 (21% identical). Paralogues in human: TOR1AIP2 (32% identical).
Diseases named in the same sentence as TOR1AIP1 in open-access papers:
TOR1AIP1 is named in the same sentence as 33 diseases in open-access papers, as found by Europe PMC text mining. Sharing a sentence is not in itself a finding about the gene and the disease. The quoted sentences say what the papers report.
muscular dystrophy (12 papers, 2019 to 2024). Muscular dystrophy (MD) refers to a group of more than 30 genetic diseases characterized by progressive weakness and degeneration of the skeletal muscles that control movement. "The clinical spectrum of diseases related to mutations in TOR1AIP1 is broad, including muscular dystrophy, congenital myasthenic syndrome, cardiomyopathy, and multisystemic disease with or without progeroid features." (PMID 37108075, 2023). "Supporting the idea that interrupting the Torsin/cofactor interaction is detrimental are reports of patients with mutations in the LAP1 gene, TOR1AIP1, who display dystonic-like symptoms, cardiomyopathy, deafness, and muscular dystrophy." (PMID 32204310, 2020). "In four previous reports of TOR1AIP1 mutations in a total of 12 individuals, clinical features range from a relatively mild muscular dystrophy to a severe multi-system phenotype." (PMID 33215087, 2020). "A clinical feature in common for TOR1AIP1 mutations is a muscular dystrophy, which is also present in the conditional M-LAP1−/− mouse model." (PMID 33215087, 2020). "The remaining six families had pathogenic variants in genes usually associated with muscular dystrophies (HNRNPDL, TOR1AIP1, SGCG, COL6A2, CAV3, TRIP4)." (PMID 38982518, 2024). "These torsins preserve the nuclear envelope membrane integrity and require direct contact with TOR1AIP1/LAP1; mutations affecting this direct contact result in dystonia, muscular dystrophy, cardiomyopathy, and deafness." (PMID 34659373, 2021). "In particular, genetic alterations in the human TOR1AIP1 gene, which encodes lamina-associated polypeptide 1 (LAP1), have collectively been implicated in severe cases of cardiomyopathy, muscular dystrophy, dystonia and brain atrophy." (PMID 32751253, 2020). "Since then, muscular dystrophy has been described in six other patients with TOR1AIP1 mutations who do not necessarily share all features reported in the original patient." (PMID 37108075, 2023). "Biallelic variants in TOR1AIP1, encoding the integral nuclear membrane protein LAP1 (lamina-associated polypeptide 1) with two functional isoforms LAP1B and LAP1C, have initially been linked to muscular dystrophies with variable cardiac and neurological impairment." (PMID 32055997, 2020). "In addition to dystonia-like symptoms, recessive mutations in TOR1AIP1 that disrupt the LAP1B isoform have been linked to familial cardiomyopathy and muscular dystrophy." (PMID 33076344, 2020). "Notably, increased chromatin condensation and heterochromatin detachment from the INM have been observed in skeletal muscle samples from TOR1AIP1 patients with muscular dystrophy and congenital myasthenic syndrome, respectively, thus strengthening the link between LAP1 and heterochromatinization." (PMID 39769001, 2024).
Dystonia (9 papers, 2013 to 2024). An abnormally increased muscular tone that causes fixed abnormal postures. "A second TOR1AIP1 mutation (“Maroccan” mutation) was reported in a boy, born from consanguineous healthy parents, who developed rapidly progressing dystonia, progressive cerebellar atrophy, and dilated cardiomyopathy." (PMID 26784240, 2016). "Interestingly, one patient carrying a TOR1AIP1 mutation affecting the torsinA binding domain of LAP1 presented with dystonia, dilated cardiomyopathy, and cerebellar atrophy." (PMID 37108075, 2023).
cardiomyopathy (8 papers, 2014 to 2023). A disease of the heart muscle or myocardium proper. "Evidence collected to date suggests an association between the location and the type of mutation in TOR1AIP1 with clinical presentation, which ranges from isolated cardiomyopathy to fatal progeroid-like multisystemic disorders." (PMID 37108075, 2023). "TOR1AIP1 mutations have been reported in patients with skeletal muscle disorders with or without cardiomyopathies." (PMID 37108075, 2023). "The first mutation in TOR1AIP1 was identified in a family affected by progressive muscular dystrophy, joint contractures, and cardiomyopathy, which leads to the complete absence of LAP1B while expression of LAP1C is preserved." (PMID 36362402, 2022).
congenital myasthenic syndrome (3 papers, 2020 to 2024). Congenital myasthenic syndrome (CMS) is a group of genetic disorders of impaired neuromuscular transmission at the motor endplate characterized by fatigable muscle weakness. "The link between LAP1 and neuromuscular transmission is suggested by the congenital myasthenic syndrome (CMS) phenotype that was first described in two patients with TOR1AIP1 mutations." (PMID 37108075, 2023). "A mutation in TOR1AIP1 causes a new type of congenital myasthenic syndrome, characterized by limb girdle fatiguable muscle weakness and compound muscle action potential decrement on repetitive nerve stimulation." (PMID 33215087, 2020). "Here, we describe a congenital myasthenic syndrome due to a mutation in TOR1AIP1, which encodes LAP1, a nuclear envelope protein." (PMID 33215087, 2020). "In summary we describe here an autosomal recessive congenital myasthenia caused by mutations in TOR1AIP1, encoding a nuclear envelope protein." (PMID 33215087, 2020).
cataract (2 papers, 2020 to 2024). Partial or complete opacity of the crystalline lens of one or both eyes that decreases visual acuity and eventually results in blindness. "Other TOR1AIP1 mutations manifest as a progeroid-like multisystemic condition (including, but not limited to, progressive neurological deterioration, cardiac/skeletal muscle defects and cataracts) or as striated muscle disorders [13,16,]." (PMID 39035020, 2024).
limb-girdle muscular dystrophy (2 papers, 2020 to 2022). Limb-girdle muscular dystrophy (LGMD) is a heterogeneous group of muscular dystrophies characterized by proximal weakness affecting the pelvic and shoulder girdles. "Variants of this gene have been identified in limb-girdle muscular dystrophy, and TOR1AIP1 knockout in striated muscle results in muscle weakness." (PMID 35852874, 2022). "Rare recessive mutations in TOR1AIP1 have been reported to cause limb-girdle muscular dystrophy or dystonia, with cardiomyopathy or a severe multisystem disorder." (PMID 33215087, 2020). "Rare mutations in TOR1AIP1 have been described giving rise to a limb girdle muscular dystrophy phenotype with cardiac involvement, but with no report of defective neuromuscular transmission." (PMID 33215087, 2020).
vitiligo (2 papers, 2022). Generalized well circumscribed patches of leukoderma that are generally distributed over symmetric body locations and is due to autoimmune destruction of melanocytes. "Retinol binding protein-1, torsin 1A interacting protein 1 and protein disulfide-isomerase A4 were validated to have the potential to reflect positive treatment effect to GCs treatment in active vitiligo with AUC value of 0.861, 1 and 0.868, respectively." (PMID 35252347, 2022).
breast carcinoma (1 paper, 2020). "Interestingly, we observed mutant protein expression of Replication Timing Regulatory Factor 1 (RIF1) and Torsin-1A-interacting protein 1 (TOR1AIP1) across all four breast cancer cell lines." (PMID 33274046, 2020).
Cirrhosis (1 paper, 2012). A chronic disorder of the liver in which liver tissue becomes scarred and is partially replaced by regenerative nodules and fibrotic tissue resulting in loss of liver function. "Most cell structure related genes were up-regulated in initial fibrosis (HYLS1, MAP6D1 and TOR1AIP1) and genes related to cell adhesion, cell cycle and signaling showed differential expression in both initial fibrosis and cirrhosis." (PMID 22397681, 2012).
generalized dystonia (1 paper, 2018). "Recessive mutations of TOR1AIP1 (OMIM 614512) which encodes LAP1 are associated with severe early‐onset generalized dystonia and progressive cerebellar atrophy." (PMID 29770609, 2018).
kidney failure (1 paper, 2020). An acute or chronic condition that is characterized by the inability of the kidneys to adequately filter the blood. "The fulminant cardiac crisis, accompanied by kidney failure in individual 1 and death in individual 2, further highlights the importance of tight cardiac surveillance for TOR1AIP1 mutated individuals." (PMID 32055997, 2020).
melanoma (1 paper, 2023). A malignant, usually aggressive tumor composed of atypical, neoplastic melanocytes. "Of the two LAP1 isoforms encoded by TOR1AIP1, the short isoform (LAP1C) could be localized to and could support the biogenesis of NE blebs, suggesting a bleb-permissive LAP1C-phenotype may predominate in invasive melanoma with elevated levels of this protein." (PMID 36624187, 2023). "Furthermore, using publicly available patient datasets (Kabbarah41, Riker42 and Xu43), we found that TOR1AIP1 messenger RNA levels were consistently upregulated in human samples obtained from metastatic melanoma lesions compared with primary melanoma." (PMID 36624187, 2023).
scleroderma (1 paper, 2020). Scleroderma is a rare autoimmune connective tissue disorder characterized by abnormal hardening of the skin and, sometimes, other organs. "Mandibular hypoplasia with dental crowding and irregular teeth, scleroderma-like skin changes, Raynaud’s phenomenon, most of which are commonly observed in other segmental progeroid syndromes, have not been previously associated with TOR1AIP1 before." (PMID 32055997, 2020).
cancer (4 papers, 2021 to 2024). A tumor composed of atypical neoplastic, often pleomorphic cells that invade other tissues. "ESR1, TOR1AIP1, STAT1, COL1A1 were identified as high expression, while EGFR, AR, GATA2 were identified as a low expression in both cancer types." (PMID 33907495, 2021). "With the exception of TOR1AIP1 and PRR5L, almost all other hub genes have been reported to be involved in cancers." (PMID 33987007, 2021).
tumor (3 papers, 2021 to 2024). "Moreover, it has recently been found that TOR1AIP1 expression is significantly altered in various tumor types and that LAP1 upregulation can contribute to an enhanced migratory and invasive ability of melanoma cells, which indicates that LAP1 may also be involved in cancer." (PMID 39035020, 2024). "Through a systems medicine approach, it was determined that hub biomolecules, AR, GATA2, miR-124, TOR1AIP1, ESR1, EGFR, STAT1, miR-192, GATA3, COL1A1, in tumor microenvironment generic network." (PMID 33907495, 2021). "These hub biomolecules of tumor stroma network, AR, GATA2, miR-124, TOR1AIP1, ESR1, EGFR, STAT1, miR-192, GATA3, COL1A1, may give crucial information about tumorigenesis." (PMID 33907495, 2021).
inherited disease (1 paper, 2020). "It is an autosomal recessive-inherited disease caused by a mutation in the torsinA-interacting protein 1 (TOR1AIP1) gene, which encodes lamina-associated polypeptide 1 (LAP1), a nuclear envelope protein." (PMID 32873274, 2020).
TOR1AIP1 also shares sentences with these, for which no sentence is quoted: Cerebellar atrophy (5 papers); dilated cardiomyopathy (2); Skeletal myopathy (2); Brain atrophy (1); cervical cancer (1); Childhood onset (1); chronic heart failure (1); deafness (1); familial cardiomyopathy (1); fibrosis (1); infection (1); microcephaly (1); muscular atrophy (1); myopathy (1); progressive muscular dystrophy (1); skin changes (1); skin melanoma (1).